RNU6-1260P (RNA, U6 small nuclear 1260, pseudogene)
Gene: Small nuclear RNA gene on chromosome 9 (14,850,429 to 14,850,535, forward strand). Ensembl gene ENSG00000199814.
Homologues: Orthologues: chimpanzee U6 (98% identical), macaque U6 (95% identical), rat U6 (92% identical), dog U6 (85% identical), guinea pig U6 (83% identical), rabbit U6 (83% identical), pig U6 (79% identical). Paralogues in human: RNU6-21P (92% identical), RNU6-61P (91% identical), RNU6-698P (90% identical), RNU6-7 (90% identical), RNU6-8 (90% identical), RNU6-80P (90% identical), RNU6-1 (89% identical), RNU6-144P (89% identical), RNU6-15P (89% identical), RNU6-19P (89% identical), RNU6-2 (89% identical), RNU6-20P (89% identical), and 1286 more.